CRP (C-reactive protein)
Diseases named in the same sentence as CRP in open-access papers (continued):
Sharing a sentence is not in itself a finding about the gene and the disease.
COVID-19 (continued). "Laboratory markers were characteristic for COVID-19, such as lymphopenia, elevated D-dimer, C-reactive protein (CRP), and interleukin 6 (IL-6)." (PMID 33732571, 2021). "Both CRP and PCT are inflammatory parameters and reported to be associated with severe illness or mortality in patients with COVID-19 in many studies." (PMID 34563117, 2021). "All out of 32 subjects who had COVID-19 showed normal inflammatory markers with normal CRP and D-dimer levels at follow-up examination." (PMID 34588541, 2021). "CRP is a regulatory factor for angiogenesis and thrombosis associated with cardiovascular disease (CVD), which is a risk factor for COVID-19 severe cases." (PMID 34691068, 2021). "In a recent systematic review, 10 of the 22 included COVID-19 prognostic models treated CRP either as a factor or covariate." (PMID 33683344, 2021). "A case report of 99 COVID-19 patients from Wuhan hospital has revealed an increase in the total number of CRP, interluekin-6 (IL-6), and neutrophils—86%, 52%, and 38%, respectively—and a 35% decrease of the total number of lymphocytes." (PMID 33498679, 2021). "COVID-19 patients present a systemic inflammatory state, as demonstrated by the significant increase of C-reactive protein (CRP), IL-6, IL-8, IL-10, IL-2R, and ferritin blood levels." (PMID 32852580, 2021). "In summary, high BMI, exposure to Wuhan, any coexisting medical condition, highest temperature, CRP and increased LDH were independent risk factors for severe/critical COVID-19 patients." (PMID 33546633, 2021). "CRP is suggested as a factor contributing to the development of severe cases of COVID-19 by inducing the production of proinflammatory cytokines, apoptosis, and the inflammatory status." (PMID 35059135, 2021). "The levels of inflammatory and coagulation markers (C-reactive protein, D-dimer, and fibrinogen) were higher in the COVID-19 group than those in the control group." (PMID 34759880, 2021). "Previous studies have reported abnormal levels of IL-2, IL-6, IL-7, IL-10, CRP, and tumor necrosis factor-α in COVID-19 patients." (PMID 34242179, 2021). "Several studies have shown alterations of some laboratory parameters with greater frequency in patients with COVID-19, such as lymphocyte count, CRP, LDH, d-dimer, and fibrinogen." (PMID 33832103, 2021). "Red cell distribution width, platelet distribution width, and C-reactive protein are useful, inexpensive, and early predictive markers of mortality in COVID-19." (PMID 33680618, 2021). "In COVID-19 adult patients, COVID-19 is typically associated with a significant degree of inflammation with an increase in interleukin 6 (IL6), C-reactive protein (CRP), fibrinogen, and erythrocyte sedimentation rate (ESR)." (PMID 34822379, 2021). "In conclusion, our study showed independent predictors for mortality among hospitalized COVID-19 patients by sex, including presence of public insurance type, qSOFA, and elevated CRP in both sexes." (PMID 36168478, 2021). "Another inflammation indicator used to predict worsening clinical condition in COVID-19 patients is the C-reactive protein (CRP) level." (PMID 33628506, 2021). "During the COVID-19 pandemics, clinicians are eager to find biomarkers that can differentiate between AOSD and COVID-19, particularly in febrile patients with elevated C-reactive protein (CRP) or hyperferritinemia." (PMID 34367188, 2021). "This hyperinflammation in severe COVID-19 patients includes elevated levels of C-reactive protein (CRP), ferritin, fibrinogen and D-dimers." (PMID 33684134, 2021). "This study emphasizes that high BMI, elderly age, high CRP and 4C-scores correlate with the severity and mortality of COVID-19 patients." (PMID 34822419, 2021). "Serum LDL-C levels of COVID-19 patients was negatively correlated with CRP level, but positively correlated with lymphocyte count." (PMID 34124081, 2021).
COVID-19 (continued). "Various laboratory parameters such as high c-reactive protein (CRP), low albumin and leukocyte levels were found characteristic for COVID-19, whereas higher age, obesity, hypertension, and high CRP concentrations were associated with poor outcome." (PMID 34204453, 2021). "CRP and ferritin are used to classify COVID-19 hyper-inflammation and work also as predictors of treatment escalation." (PMID 34480127, 2021). "A controlled study with 314 confirmed symptomatic cases of COVID-19 reported that patients with eosinophilia had lower levels of CRP, milder clinical courses, and better disease outcomes than those without eosinophilia." (PMID 34578258, 2021). "Leukocytopenia, lymphopenia, and elevated C-reactive protein (CRP) can occur in the primary form of COVID-19." (PMID 33781275, 2021). "IL-6 and D-dimer were also shown to be greater in COVID-19 non-survivors vs. survivors, and higher levels of the acute phase proteins CRP and SAA in plasma have been associated with more severe disease and poorer outcomes in patients with COVID-19." (PMID 33800954, 2021). "CRP was positively associated with IFNγ, IL-2, TNFα IL-1α IFNβ IL-6 IL-17A IL-10, CXCL-10 and VEGF in children with PIMS-TS and COVID-19." (PMID 33813138, 2021). "For instance, a recent study demonstrated a heterogeneous CRP response among patients with COVID-19, with some patients with severe outcomes presenting with increased CRP levels and others presenting with increased neutrophil counts." (PMID 34683115, 2021). "This agrees with demonstrations of elevated values for CRP, D-Dimer, IL-6, and ferritin in COVID-19 patients." (PMID 34510338, 2021). "Furthermore, although the finding of an association between circulating CRP level and PE in the present study may suggest superimposing bacterial infection, evidence from autopsy of COVID-19 patients implicated the role of platelet activation rather than infectious pathogens in thrombosis formation." (PMID 34362946, 2021). "In a follow-up study including 384 hospitalized COVID-19 patients, the D-dimer, CRP, and ferritin levels normalized within two months after discharge." (PMID 34677197, 2021). "In a meta-analysis of 86 studies, severe COVID-19 was strongly associated with lymphocytopenia, hyperglycemia, ARDS, and high levels of interleukin (IL)-6 and C-reactive protein (CRP)." (PMID 33530554, 2021). "In agreement with this, patients with severe COVID-19 presented high levels of d-dimer, serum ferritin, IL-6 and C-reactive protein." (PMID 33709775, 2021). "The result of this study, which included patients with severe forms of COVID-19 admitted to a tertiary center, is in line with previous reports confirming the independent relationship between CRP, D-Dimer, and mortality in COVID-19." (PMID 35011795, 2021). "The most-reported predictors of severe progression in patients with COVID-19 included age, sex, features derived from computed tomography scans, C reactive protein, lactic dehydrogenase, and lymphocyte count." (PMID 33536460, 2021). "We found a higher level of WBC, NEU, and CRP in patients with leptospirosis, while the average level of these biomarkers on COVID-19 cases remained in the relatively normal range." (PMID 33869775, 2021). "Higher levels of AST and CRP were also found in refractory patients compared with general COVID-19 patients." (PMID 34035353, 2021). "The results of our study showed that the total bilirubin levels, which are an indicator of HO-1 enzyme activity, and the CRP levels were independent predictors of myocarditis in COVID-19 patients." (PMID 34928467, 2021). "Furthermore, the association between raised CRP and increased risk of COVID-19 severity and death observed in this study has also been observed in other studies, as might be expected for a biomarker associated with the severity of infectious and inflammatory diseases in general." (PMID 34400804, 2021).
COVID-19 (continued). "Currently, serum IL-6 level, along with other inflammatory markers such as CRP, ferritin, are used in isolation or together to determine and predict the efficacy of tocilizumab in COVID-19 treatment." (PMID 34001244, 2021). "Least absolute shrinkage and selection operator (LASSO) regression has identified age, neutrophil-to-lymphocyte ratio (NLR), D-dimer, and C-reactive protein (CRP) recorded during admission as mortality predictors for COVID-19 patients." (PMID 33897907, 2021). "Some reports also found the appearance of lymphopenia as well as high levels of D-dimer and C-reactive protein in COVID-19 patients." (PMID 34746417, 2021). "The results revealed that CRP, D-dimer, LDH levels, and lymphopenia have a significant association with the COVID-19 severity and can be used as biomarkers to predict the disease severity." (PMID 33861750, 2021). "Lower levels of fetuin-A observed in COVID-19 patients despite higher HOMA-IR, CRP, and ferritin levels, pneumonia, patients requiring ICU care suggests that fetuin-A deficiency predisposes to more severe COVID-19 course." (PMID 34680053, 2021). "Longitudinal studies have demonstrated gradual declines of serum concentration of inflammatory biomarkers including IL-6, IL-8, tumor necrosis factor-α, and high-sensitivity C-reactive protein (hs-CRP) at the late stage of illness in COVID-19 survivors." (PMID 34912863, 2021). "The ROC curve was used to make positive and negative predictions, suggesting that increases in Alb and Hct but decreases in CRP, PCT, LDH, HBDH, and ESR were more susceptible to COVID-19." (PMID 34859002, 2021). "In patients diagnosed with COVID-19, laboratory findings that were commonly present included lymphopenia, raised CRP levels and raised LDH levels." (PMID 33482780, 2021). "CRP, neutrophils, and procalcitonin were correlated with the volumes of pneumonia in patients who died from COVID-19, which indicated that these inflammation-related biomarkers were involved in the development of lung inflammation." (PMID 34400884, 2021). "High BMI, exposure to Wuhan, any coexisting medical condition, high temperature, C-reactive protein (CRP), and increased lactate dehydrogenase (LDH) were independent risk factors for severe/critical COVID-19." (PMID 33546633, 2021). "Overall, COVID-19 patients were characterized by hyperfibrinogenemia, marked increased D-dimer levels, and increased C-reactive protein (CRP)." (PMID 33923851, 2021). "The authors drew a roadmap, indicating that patients with CRP > 41.8 mg/L were more prone to developing severe COVID-19 illness." (PMID 33808934, 2021). "A number of additional biomarkers were nominally significantly different between groups (p < 0.05) with Ang-1, bFGF, Eotaxin-3 and CRP being higher in COVID-19, while sTie-2 and sTREM-1 were lower in COVID-19." (PMID 33874973, 2021). "In our study, high C-RP levels differ statistically between the ambulatory, hospitalized, and dead patients, which suggested that CRP is a marker of disease aggravation in COVID-19 patients; these results stand accordingly with other published studies." (PMID 34451520, 2021). "The association between high serum levels of CRP and ESR and COVID-19 progression and severity of the disease is known." (PMID 33957992, 2021). "On admission, SARS-CoV-2 was detected on a nasopharyngeal swab, CRP and procalcitonin were elevated (101 mg/L and 3.17 ng/mL respectively) and chest radiograph revealed changes consistent with COVID-19." (PMID 34969393, 2021). "Comparing plasma proteins positively correlated with either CRP levels, SOFA- or WHO scores, we detected an intersection of seven shared plasma proteins, representing the core signature associated with severe COVID-19." (PMID 34893580, 2021). "COVID-19 patients at admission showed lower leukocytes count (including eosinophils, basophils, and lymphocytes counts: p < 0.005) and higher CRP values (p = 0.005)." (PMID 34064556, 2021).
COVID-19 (continued). "Very few studies have examined the association of these monocyte activation markers (with the exception of CRP) in COVID-19." (PMID 34642411, 2021). "In other words, ROC analysis confirmed CRP as a valuable predictor of COVID-19 progression and severity." (PMID 33968148, 2021). "LDH and CRP are markers of acute inflammation and hypoxia in COVID-19 patients and increased levels of CRP and LDH correlate with increased severity of illness and increased risk of death." (PMID 34692345, 2021). "Patients with older age, higher RR, lower sO2 and DBP, higher creatinine, d-dimer, INR, CRP, procalcitonin, ferritin, and fibrinogen on initial admission were found to be less likely to survive COVID-19." (PMID 33564550, 2021). "According to existing data, IL-6 surpasses CRP and other inflammatory indicators in predicting respiratory failure in COVID-19." (PMID 34966605, 2021). "Elevated D-dimer and CRP levels in the first week of admission were associated with both higher hospital mortality and higher incidence of VTE and COVID-19 systemic inflammation in the adjusted analyses." (PMID 34909913, 2021). "CRP, which is commonly found as a result of inflammation and tissue damage has also been observed to be upregulated in COVID-19 patients." (PMID 34714894, 2021). "Except for P3, all patients with a mild or moderate course of COVID-19 (P1–10) had very high CRP (> 100 mg/l) levels on admission, indicative of generalized high-grade inflammation; however, the CRP levels of these patients decreased after one week." (PMID 33903660, 2021). "CRP apheresis provides a therapeutic approach to rapidly decrease the high CRP levels in COVID-19 patients before lung deterioration can progress." (PMID 33679775, 2021). "CT scanning is regarded as providing one of the crucial criteria in the diagnosis of COVID-19, and hyper-sensitive-CRP (hs-CRP) is a sensitive indicator of the degree of inflammation." (PMID 34689717, 2021). "Our results suggest that IL-6, which is the key cytokine located upstream of the inflammatory cytokine cascade, increases prior to ARDS in critical COVID-19 patients, followed by an increase in acute-phase protein levels, such as CRP." (PMID 34441262, 2021). "In conclusion, we show that the dynamic changes in CRP concentrations over time can be predictive of both, microbiological and survival outcomes in the context of COVID-19 in our patient group." (PMID 34496795, 2021). "CRP concentrations were higher over time in COVID-19 patients with positive microbiology (day 9: 236 vs 123 mg/L, p < 0.0001) and in those who died (day 8: 226 vs 152 mg/L, p < 0.0001) but only after day 7 of COVID-related symptom onset." (PMID 34496795, 2021). "Our study was able to identify certain features that were dominant in COVID-19 patients when juxtaposing both groups: Patients with confirmed COVID-19 were more likely to have fever and showed significantly higher values of CRP and LDH." (PMID 33568104, 2021). "The use of IFN-α2-β in combination with Arbidol significantly reduced the virus persistence in the upper respiratory tract and shortened the presence of the inflammatory markers IL-6 and CRP in adults hospitalized with COVID-19 at the same time." (PMID 34603758, 2021). "In COVID-19, both the lymphocyte count and the CRP level have been reported to be inflammatory markers for poor outcomes." (PMID 34342755, 2021). "COVID-19 patients with hs-CRP > 31.10 (mg/l) had inferior outcomes with median OS times of 9 days (95% CI, 7 to 10) and 20 days (95% CI, 15 to NR) and OS rates of 25.0% and 50.0% in cohort 1 and 2, respectively." (PMID 34777350, 2021). "A recent systematic review and meta-analysis confirmed that elevated CRP levels are predictors of a worse prognosis in COVID-19 patients." (PMID 34568363, 2021). "This is different from our current data, in which elevated CRP was a strong predictor of hypoxemia after hospitalization for COVID-19." (PMID 34441877, 2021).
COVID-19 (continued). "Based on the findings of the present study, the laboratory profile of pregnant women with COVID-19 is similar to that of the control group except for C-reactive protein concentration, ALT, and AST (p < 0.05)." (PMID 34149282, 2021). "Various COVID-19 prognostic indicators have been described in the literature, such as neutrophil:lymphocyte ratio, CRP, age, gender, ethnicity, oxygen saturation on admission, diabetes mellitus, hypertension, malignancy, obesity and COPD." (PMID 34207560, 2021). "The IDSA guidelines recommend tocilizumab more liberally to also include patients with progressive severe COVID-19 requiring supplemental oxygen with a CRP ≥75 mg/L." (PMID 34578287, 2021). "Although, in the CORONET study, high CRP levels were considered the most important feature in predicting COVID-19 severity." (PMID 34400804, 2021). "Creatinine, Lactate Dehydrogenase (LDH) levels, Lymphocyte count, D-Dimer, Troponin, IL-6 and CRP are shown to be important biomarkers for the severity prognosis of COVID-19." (PMID 34573923, 2021). "For example, C-reactive protein was shown to be a marker for disease severity, even the in early stages of COVID-19." (PMID 34305826, 2021). "Increased C-reactive protein concentration was evident in most patients (236/291, 81.1%), but it was more likely to be increased in influenza A patients (93.8%) than in COVID-19 patients (68.3%) (OR 0.1, 95% CI 0.0–0.3)." (PMID 34447759, 2021). "Elevation of common parameters associated with inflammation, such as CRP, procalcitonin (PCT), and cytokines, is very frequently found in COVID-19." (PMID 33747583, 2021). "The severity of COVID-19 is correlated with the levels of interleukin (IL)-6, C-reactive protein (CRP), and other proinflammatory cytokines." (PMID 33029758, 2021). "Further analysis indicated that cystatin C was negatively correlated with IL-6 (r=− 0.472, P=0.001) and eGFR was inversely correlated with CRP (r=− 0.210, P=0.012) among COVID-19 patients." (PMID 33557785, 2021). "Certain clinical parameters such as Neutrophils to Lymphocytes ratio (NLR), C-reactive protein (CRP) and D-dimer have been associated with severity of COVID-19." (PMID 34746027, 2021). "Both those parameters were correlated (r = 0.424; p < 0.001), and GDF-15 levels also correlated with other biomarkers of COVID-19 severity/mortality, namely, IL-6, CRP, ferritin, D-dimer and neutrophils, and inversely with lymphocyte count." (PMID 34829345, 2021). "We previously investigated the natural course of PCT and CRP and their value to identify secondary infections in critically ill COVID-19." (PMID 34353339, 2021). "Hospitalized COVID-19 patients with acute disease showed significantly higher levels of inflammatory markers (CRP, IL-6) compared to convalescent patients and healthy controls as sign of inflammation due to acute viral infection." (PMID 34835130, 2021). "In adults, according to the study of 99 COVID-19 patients with mean age of 55 and mostly men 68%, the disease in laboratory tests manifests by an increase in the total number of C-reactive protein (CRP), Interluekin-6 (IL-6), neutrophils, and leucocytes." (PMID 34063964, 2021). "In our study, although LDH, CHE, and CRP levels were significantly different between patients with severe and critical COVID-19 indicating their potential as parameters for severity, the d-dimer levels were not significantly different." (PMID 34399775, 2021). "A study reported lower mortality in COVID-19 patients with reduced CRP level than persistently high CRP level." (PMID 33638944, 2021). "Serum LDL-C levels of COVID-19 patients was negatively correlated with CRP level, but positively correlated with lymphocyte count, as shown by Pearson correlation analysis." (PMID 34124081, 2021). "As for COVID-19 presentation, a CURB-65 score of ≥3 as well as lower platelet count, lower hemoglobin, elevated d-dimer, CRP >10 mg/dL, and LDH >300 U/L were associated with an increased risk of death (P < 0.05)." (PMID 33604516, 2021).